CXCL16 (C-X-C motif chemokine ligand 16)
Diseases named in the same sentence as CXCL16 in open-access papers (continued):
Sharing a sentence is not in itself a finding about the gene and the disease.
infectious disease (1 paper, 2020). A disorder directly resulting from the presence and activity of a microbial, viral, or parasitic agent in humans. "In fact, in infectious diseases dysregulation of numerous ADAM substrates such as junction molecules (e.g., E-cadherin, VE-cadherin, JAM-A), adhesion molecules (e.g., ICAM-1, VCAM-1, L-selectin), and chemokines and cytokines (e.g., CXCL16, TNF-α) has been observed." (PMID 33392273, 2020).
CXCL16 also shares sentences with these, for which no sentence is quoted: Autoimmunity (3 papers); lymph node metastasis (3); schwannoma (3); Ureteral obstruction (3); acute tubular necrosis (2); colorectal (2); dementia (2); end-stage renal disease (2); endothelial dysfunction (2); metabolic disorders (2); non-alcoholic fatty liver disease (2); osteoarthritis (2); pneumonia (2); primary biliary cholangitis (2); pseudoexfoliation glaucoma (2); pustular psoriasis (2); renal failure (2); acne vulgaris (1); acute myocardial infarction (1); airway hyperresponsiveness (1); Alcohol (1); Allergy (1); alopecia (1); aortic valve disease (1); Atrophy (1); autoimmune hepatitis (1); babesiosis (1); benign tumor (1); biliary atresia (1); bipolar disorder (1).
A further 63 diseases each share a sentence with CXCL16 in 1 paper.